PIEZO1 (piezo type mechanosensitive ion channel component 1 (Er blood group))
Diseases named in the same sentence as PIEZO1 in open-access papers (continued):
Sharing a sentence is not in itself a finding about the gene and the disease.
hereditary stomatocytosis (10 papers, 2015 to 2025). "Gain-of-function PIEZO1 mutations are linked with red blood cell (RBC) dehydration (also known as xerocytosis or dehydrated hereditary stomatocytosis), highlighting an important role of PIEZO1 in mediating RVD in RBCs." (PMID 39936392, 2025). "Loss-of-function mutations in human PIEZO1 results in autosomal recessive congenital lymphatic dysplasia, and gain-of-function mutations of PIEZO1 cause the disease dehydrated hereditary stomatocytosis." (PMID 35586339, 2022). "Dehydrated hereditary stomatocytosis (DHSt) caused by PIEZO1 mutations was characterized by left-shifted curve, whereas KCNN4 mutations were associated with a normal curve." (PMID 29755372, 2018). "Gain-of-function mutations in PIEZO1 cause an autosomal dominant haemolytic anaemia in humans called dehydrated hereditary stomatocytosis." (PMID 26387913, 2015). "One of these variants, 16:88719665:G:A or T2127M (rs587776991) is a gain of function variant that slows down inactivation kinetics of PIEZO1 in patients with dehydrated hereditary stomatocytosis (a disorder of red blood cells), together with other gain of function variants." (PMID 36088354, 2022). "This novel erythrocyte trait, sharing features with both hereditary spherocytosis and overhydrated hereditary stomatocytosis, complements the clinical features associated with loss-of-function mutations of PIEZO1 in the context of the generalized lymphatic dysplasia of LMPH3 type." (PMID 30930797, 2019). "The potential role of Piezo1 in RBC physiology is most clearly demonstrated by many gain-of-function mutations in Piezo1 that have been identified in patients with the RBC disease xerocytosis, also called dehydrated hereditary stomatocytosis (DHS)." (PMID 26001274, 2015).
sickle cell disease (10 papers, 2015 to 2026). Sickle cell anemias are chronic hemolytic diseases that may induce three types of acute accidents: severe anemia, severe bacterial infections, and ischemic vasoocclusive accidents (VOA) caused by sickle-shaped red blood cells obstructing small blood vessels and capillaries. "Genetic diseases such as Piezo1‐R2456H and Piezo1‐M2225R mutants are associated with sickle cell anemia, affecting the homeostasis of red blood cell volume." (PMID 39488795, 2024). "The current investigation is focused on the magnitude, kinetics, and implications of the pump-leak fluxes induced by deoxy-Piezo1 channels on the pathophysiology of sickle cell disease." (PMID 41964222, 2026). "Significant relevance has also been ascribed to RBC-Piezo1 in the special case of sickle cell disease (SCD), and recent computational modeling studies have enabled tracking of Piezo1-dependent processes across the RBC lifespan." (PMID 40929564, 2025). "In sickle cell disease, Piezo1 stimulation decreases sickle RBC deformability and increases the cell propensity to sickle upon deoxygenation and to adhere to laminin." (PMID 38254651, 2023). "The effects of Yoda1, a pharmacological activator of PIEZO1, were investigated on intracellular [Ca2+] ([Ca2+]i) and phosphatidylserine (PS) exposure in red cells from patients with sickle cell anaemia (SCA)." (PMID 33208899, 2020). "For example, studies have found that HBS aggregation can activate Piezo1, thereby increasing intracellular calcium ion concentration, ultimately increasing the number of sickle red blood cells and promoting the progression of sickle cell anemia." (PMID 38690080, 2024). "In particular, many believe that Piezo1 may be involved in sickle cell disease, a possibility that can now be tested using the tools described in this study." (PMID 26001274, 2015). "Targeting Piezo1 may be a promising treatment for sickle cell anemia." (PMID 38690080, 2024). "Piezo1 has been proposed by many to mediate a non-selective current observed in sickle cell disease (SCD) called PSickle, which acts upstream of KCa3.1 to mediate RBC sickling." (PMID 26001274, 2015).
synovial sarcoma (10 papers, 2018 to 2024). "A study of Piezo1 and cell viability in synovial sarcoma showed that reducing the expression of Piezo1 caused a significant reduction in cell viability as well." (PMID 34831037, 2021). "In synovial sarcoma, Piezo1 is highly expressed in SW982 cells, and knocking it down affects cell viability, making it a potential target against synovial sarcoma." (PMID 38690080, 2024). "In one study of the SW982 synovial sarcoma cell line, Piezo1 knockdown resulted in decreased cell migration." (PMID 34831037, 2021). "In the present study, we examined the possibility that PIEZO1 is involved in the regulation of synovial sarcoma cell-viability." (PMID 29757938, 2018). "To test the function of PIEZO1 in synovial sarcoma, we next knocked down PIEZO1 in SW982 cells using stealth small interfering RNA (siRNA)." (PMID 29757938, 2018). "Here, we examined the possibility that PIEZO1 is involved in the regulation of synovial sarcoma cell-viability." (PMID 29757938, 2018). "In this study, we found that synovial sarcoma SW982 cells express PIEZO1, which is effectively activated by Yoda1 in a concentration-dependent manner." (PMID 29757938, 2018). "Our results provide new insights into PIEZO1 function showing that this mechno-sensing channel is highly expressed in synovial sarcoma SW982 cells and can regulate their cell-viability." (PMID 29757938, 2018). "Here, by employing PIEZO1 agonist Yoda1 and siRNA technology, we demonstrate that PIEZO1 is highly expressed in human synovial sarcoma SW982 cells and its knockdown affects the cell-viability." (PMID 29757938, 2018). "Piezo1 is closely related to a variety of human tumors, such as synovial sarcoma." (PMID 33575334, 2021). "Piezo1 is a potential regulator of synovial sarcoma cell viability and may play a role in invasion and metastasis proliferation." (PMID 33575334, 2021). "In contrast, PIEZO1 knockdown reduced the proliferation of human synovial sarcoma SW982 cells." (PMID 31597314, 2019). "In addition, Yoda1 caused the activation of cation channel currents in both cell types, strongly suggesting that synovial sarcoma SW982 cells express functional PIEZO1." (PMID 29757938, 2018). "The molecular mechanisms underlying the anti cell-viability in synovial sarcoma without PIEZO1 are yet to be elucidated and potentially involve the inhibition of cell adhesion." (PMID 29757938, 2018). "It has been found that Piezo1 could regulate synovial sarcoma cell viability." (PMID 32152662, 2020). "PIEZO1 knockdown in SW982 cells effectively reduced cell-viability, suggesting that this protein is a functional regulator of cell-viability in SW982 synovial sarcoma cells." (PMID 29757938, 2018). "Because PIEZO1 is highly expressed in SW982 cells and its knockdown affects cell-viability, this gene is a potential target against synovial sarcoma." (PMID 29757938, 2018). "Application of a PIEZO1 agonist Yoda1 effectively induced Ca2+ response and cation channel currents in PIEZO1-expressing HEK (HEK-Piezo1) cells and synovial sarcoma SW982 (SW982) cells." (PMID 29757938, 2018). "Because cell-viability was effectively inhibited in SW982 cells lacking functional PIEZO1 in the present study, PIEZO1 is a potential novel target against synovial sarcoma." (PMID 29757938, 2018). "In fact, our previous study revealed that PIEZO1 knockdown reduced the proliferation of the human synovial sarcoma SW982 cells, while the activation of PIEZO1 by Yoda1 failed to change the proliferation." (PMID 31597314, 2019).
atrial fibrillation (9 papers, 2021 to 2025). A disorder characterized by an electrocardiographic finding of a supraventricular arrhythmia characterized by the replacement of consistent P waves by rapid oscillations or fibrillatory waves that vary in size, shape and timing and are accompanied by an irregular ventricular response. "Atrial fibrillations have long been associated with increased atrial stretch and dilatation, and as such, mechanosensitive ion channels such as PIEZO1 could be involved in this pathology." (PMID 37047693, 2023). "PIEZO1 overexpression, designed to mimic PIEZO1 upregulation observed in patients with atrial fibrillation, increased the stiffness of cultured cardiac fibroblasts and the stiffness of nearby fibroblasts that were not overexpressing PIEZO1." (PMID 40721314, 2025). "In individuals with non-persistent atrial fibrillation, both the activity and expression of Piezo1 are significantly increased, suggesting its predominant role over other channels compared to sinus rhythm." (PMID 39981174, 2025). "PIEZO1 channel currents in cardiac fibroblasts from patients were found to be larger when the patients had atrial fibrillation." (PMID 40721314, 2025). "Similarly, activated PIEZO1 induces the downregulation of L-type calcium currents in CMs, a major cause of atrial fibrillation (AF)." (PMID 39272994, 2024). "Our own data suggest that Piezo1 expression and activity are increased in fibroblasts in the context of atrial fibrillation (AF,)." (PMID 33809739, 2021). "Moreover, Piezo1 expression and activity were up-regulated in cardiac fibroblasts isolated from patients suffering from atrial fibrillation, thereby highlighting Piezo1 as a crucial player of myocardial fibrosis in arrhythmias." (PMID 40149710, 2025). "The administration of ω-3 PUFAs may affect PIEZO1 activity, prolonging action potential duration and increasing the propensity for delayed after depolarizations that trigger atrial fibrillation." (PMID 37031750, 2023). "PIEZO1 activity in atrial fibroblasts increased in people with atrial fibrillation, suggesting that PIEZO1 might contribute to the structural and electrical remodeling of the atrium." (PMID 37031750, 2023). "Although GsMtx-4 targets a number of different mechanosensitive ion channels, it is a potent PIEZO1 inhibitor, which suggests that this ion channel could be involved in the generation of atrial fibrillations in response to stretch." (PMID 37047693, 2023). "In one report, Piezo1 dysfunctional regulation was investigated within atrial fibrillation." (PMID 35897650, 2022). "Interestingly, CF isolated from atrial fibrillation patients expressed a higher level of Piezo1 expression and exhibited an increase in Piezo1 activity when compared to cells from sinus rhythm patients, indicating a potentially important role in atrial fibrillation and remodelling." (PMID 33922466, 2021). "It was observed that in non-passaged right atrial fibroblasts from atrial fibrillation (AF), patients’ Piezo1 expression and activity were higher compared to those patients in sinus rhythm (SR)." (PMID 35897650, 2022).
autoimmune disease (9 papers, 2022 to 2026). A disorder resulting from loss of function or tissue destruction of an organ or multiple organs, arising from humoral or cellular immune responses of the individual to their own tissue constituents. "These insights also identify PIEZO1 as a potential therapeutic target for modulating dysregulated IFN responses in the contexts of autoimmune diseases and autoreactive inflammation wherein a crucial role of pDC-derived type I IFNs is established." (PMID 41583391, 2026). "A similar study of Piezo1 in murine T cells showed parallel results that Piezo1cKO mice have less severe autoimmune disease." (PMID 39492686, 2025). "Therapeutic strategies targeting Piezo1 must therefore be precisely tailored to the specific pathological context, offering significant potential in the treatment of autoimmune diseases and cancer immunotherapy." (PMID 40821847, 2025). "Collectively, our data demonstrate that Piezo1 contributes to the pathogenesis of CD4+ T-cell–mediated autoimmune disease by restraining CD4+ T-cell activation and maintaining effector memory T cells." (PMID 39492686, 2025). "On one hand, Piezo1 senses mechanical stimuli and suppresses the differentiation of Th1 and Th17 cells, thereby promoting immune tolerance and preventing the development of autoimmune diseases." (PMID 40821847, 2025). "The altered expression and dysfunction of the K2P potassium ion channel family may also play a critical role in the pathophysiology of autoimmune diseases, and it is known that both Piezo1 and Piezo2 channels enhance the mechanogating of K2P channels." (PMID 37445856, 2023). "This could accelerate neuroimmune-induced sensitization on the spinal level in this autoimmune disease, with Langerhans-cell activation in the cornea and theorized downregulated Piezo1 channels in these cells." (PMID 37108693, 2023). "Collectively, these observations suggest that Piezo1 is essential for effector T-cell persistence, and without a continuous pool of newly activated CD4+ T cells, these Piezo1cKO T cells are incapable of inducing phenotypic autoimmune diseases." (PMID 39492686, 2025).
bladder cancer (9 papers, 2020 to 2026). "We demonstrate that controlled pressure activates the mechanosensitive ion channel Piezo1 in bladder cancer, triggering a calcium ion cascade that transiently and reversibly amplifies mechanosensitivity and membrane permeability." (PMID 41782384, 2026). "Studies have found that Piezo expression in human and mouse bladder cancer, and the expression of Piezo1 and Piezo2 was significantly increased in the tissues." (PMID 38362490, 2024). "The exact mechanisms of Piezo1 on bladder cancer cells are yet to be discovered; however, this channel has a positive impact on tumor stage, grade, and size." (PMID 36837670, 2023). "The pathological implications of Piezo1 and Piezo2 in bladder carcinoma in human and mice have been investigated by Etem and colleagues." (PMID 32635333, 2020). "Both Piezo1 and Piezo2 mRNA transcripts in bladder cancer tissues were found to be substantially increased in comparison with normal bladder tissues." (PMID 32635333, 2020). "If this process plays a role in tumorigenesis remains unknown, yet the number of Piezo1/2 in bladder cancer cells is significantly high." (PMID 36837670, 2023). "Little is known about the involvement of Piezo1 and 2 in bladder cancer." (PMID 36837670, 2023). "Additionally, immunohistochemical analysis of mouse bladder cancer cells revealed the overexpression of Piezo1 in the plasma membrane." (PMID 32635333, 2020).
melanoma (9 papers, 2020 to 2025). A malignant, usually aggressive tumor composed of atypical, neoplastic melanocytes. "In our study, we first identified the role of Piezo1 in melanoma in vitro and in vivo and clarified its underlying mechanisms." (PMID 36112948, 2022). "Firstly, we found that Piezo1 was upregulated in melanoma and associated with poor survival." (PMID 36112948, 2022). "Furthermore, we treated melanoma cells with Yoda1 to investigate which pathways were associated with the activation of Piezo1." (PMID 36112948, 2022). "Remarkably, lowering intracellular cholesterol levels in melanoma cells was found to de-couple the response of Piezo1 to increasing levels of confinement." (PMID 40791314, 2025). "Together, these results support a model in which mechanical stress activates PIEZO1-dependent calcium signalling to drive melanoma stem cell-like reprogramming." (PMID 40890143, 2025). "Our findings extend these observations to melanoma, demonstrating that PIEZO1 activation alone is sufficient to initiate a stem cell-like state and increase tumorigenicity." (PMID 40890143, 2025). "To test this, we investigated PIEZO1 expression and localization at the plasma membrane using immunofluorescence, noting an increase in PIEZO1 signal intensity in squeezed melanoma cells when compared to unsqueezed controls." (PMID 40890143, 2025). "PIEZO1 deletion from squeezed melanoma cells results in a significant reduction in tumorsphere formation and growth over time, with an 80% decrease in size compared to squeezed WT cells." (PMID 40890143, 2025). "Collectively, these early phosphorylation events downstream of PIEZO1 likely converge to promote transcriptional plasticity and support the emergence of a melanoma stem cell-like state." (PMID 40890143, 2025). "Together, these findings demonstrate that PIEZO1 functions as the central mechanosensor coupling transient mechanical deformation to the acquisition of the tumorigenic stem cell-like phenotype in melanoma cells." (PMID 40890143, 2025). "Here, the authors show that mechanical constriction in microcapillaries reprograms melanoma cells to a tumorigenic stem cell-like state through the mechanosensor PIEZO1." (PMID 40890143, 2025). "In serum-free culture conditions, melanoma cells exhibited consistent responses to drugs manipulating the PIEZO1 channel." (PMID 40890143, 2025). "In this article, we report the discovery that capillary-like constrictions catalyse phenotype changes in melanoma cells to a tumorigenic stem cell-like state through PIEZO1-mediated mechanotransduction." (PMID 40890143, 2025). "In melanoma cells, knockdown of Piezo1 resulted in alterations in cell cycle-related genes, with a significant decrease in the expression of key effectors CDK2 and CyclinD1 genes and an increase in the expression of classical tumor suppressors P21 and PTEN." (PMID 38690080, 2024). "The high expression of Piezo1, another important mechanosensitive Ca2+-permeable ion channel, was detected in melanoma, and was shown to correlate with its malignant progression." (PMID 37958687, 2023). "Here, we evidenced functional activity of Piezo1 channels in the aggressive human melanoma SK-MEL-2 cell line." (PMID 37958687, 2023). "We showed that the chemical activation of Piezo1 by its selective agonist, Yoda1, completely prevents melanoma spheroid formation, indicating a regulatory role of Piezo1 in this process." (PMID 37958687, 2023). "Using a combinative approach, we showed the functional expression of mechanosensitive Piezo1 channels in the aggressive human melanoma SK-MEL-2 cell line." (PMID 37958687, 2023). "Here, we uncover novel aspects of the role of the mechanosensitive ion channel Piezo1 in melanoma tumor formation." (PMID 37958687, 2023). "Mechanistically, we found that Piezo1 activated AKT/mTOR signaling to maintain malignant phenotypes of melanoma." (PMID 36112948, 2022).